LY6L (lymphocyte antigen 6 family member L)
Tractability: Antibody: UniProt places it where antibodies can reach, with medium confidence; UniProt predicts a signal peptide or a membrane-spanning region; its Gene Ontology location is reachable by antibodies, with medium confidence.
Gene: Protein-coding gene on chromosome 8 (143,080,312 to 143,083,486, forward strand). Ensembl gene ENSG00000261667.
Subcellular location: Cell membrane
Gene Ontology:
Cellular component: plasma membrane
Genetic constraint (gnomAD): Loss-of-function variants: 7 observed, 7.32 expected, observed/expected ratio (o/e) 0.96, 90% interval 0.54 to 1.7. That is too few expected variants to judge how well the gene tolerates losing a copy. Missense variants: 154 observed, 184.33 expected, observed/expected ratio (o/e) 0.84, 90% interval 0.73 to 0.95. Synonymous variants: 79 observed, 78.38 expected, observed/expected ratio (o/e) 1.01, 90% interval 0.84 to 1.22.
Homologues: Orthologues: chimpanzee LY6L (96% identical), macaque LY6L (86% identical), pig LY6L (51% identical), dog LY6L (48% identical), rat Ly6l (48% identical), mouse Ly6l (46% identical). Paralogues in human: LY6H (30% identical), LY6S (28% identical).
Diseases named in the same sentence as LY6L in open-access papers:
LY6L is named in the same sentence as 1 disease in open-access papers, as found by Europe PMC text mining. Sharing a sentence is not in itself a finding about the gene and the disease. The quoted sentences say what the papers report.
cancer (1 paper, 2024). A tumor composed of atypical neoplastic, often pleomorphic cells that invade other tissues. "Among most significantly altered genes, we selected FGF2, LY6L, and TRIM46 for further study because their gene products are known to increase the viability and malignant proliferation of cancer cells." (PMID 38600695, 2024).